CD38 (CD38 molecule)
Diseases named in the same sentence as CD38 in open-access papers (continued):
Sharing a sentence is not in itself a finding about the gene and the disease.
lung carcinoma (47 papers, 2013 to 2025). "Furthermore, in murine models of lung cancer and melanoma, acquired resistance to anti‐PD‐1/PD‐L1 agents is associated with CD38 upregulation on tumor cells, thereby leading to CD38‐mediated CD8+ T‐cell suppression via adenosine receptor signaling." (PMID 36251503, 2023). "In addition, another group showed that CD38 expression is increased following therapy with a PD-L1 inhibitor in a lung cancer mouse model, which was associated with impaired CD8+ T-cell function." (PMID 30294326, 2018). "Consistent with our study, F. Morandi concluded that inactivation of the CD38-cADPR axis might serve as a novel therapeutic intervention in lung cancer and a recent report indicated that TRPM2 was linked with poor prognosis in patients with pancreatic ductal adenocarcinoma." (PMID 34226519, 2021). "In addition, another group showed that CD38 expression is increased following therapy with a PD-L1 inhibitor in a lung cancer mouse model, which was associated with impaired CD8+ T-cell function, and the combination of a CD38 antibody with PD-L1 inhibitor showed enhanced anti-tumor activity." (PMID 32138182, 2020). "LC patients with an overall higher MAIT cell level, particularly CD38+CD8+ expression, are associated with worse progression-free survival, highlighting a detrimental role in lung cancer progression." (PMID 40746558, 2025). "Conversely, another clinical study has observed CD3+Va7.2+CD161+ MAIT cells in circulation are significantly elevated in lung cancer patients, showing an activated pro-inflammatory state by CD38+CD8+ expression." (PMID 40746558, 2025). "Compared to normal tissues, CD38 is highly expressed in primary human lung tumor tissues and metastatic lung cancer cells." (PMID 38545257, 2024). "Taken together, the data indicate that a CD38/A2AR axis regulates Snail‐dependent lung cancer cell EMT through the AKT/GSK‐3β pathway." (PMID 38545257, 2024). "Previous studies have shown that the percentage of CD8+MAIT cells was higher in the peripheral blood of patients with lung cancer, and the abundance of CD38+CD8+MAIT cells was negatively correlated with the PFS of patients with lung cancer." (PMID 38698468, 2024). "Co‐inhibition of PD‐L1 and CD38 contributed to a stronger anti‐tumor immune response compared with anti‐PD‐L1 monotherapy in a mouse lung cancer model." (PMID 36251503, 2023). "CD38 is overexpressed in several types of cancer, including prostate cancer, lung cancer, colorectal cancer, cervical cancer, and nasopharyngeal carcinoma, in which it is associated with poor prognosis 29, 69-74." (PMID 36605482, 2023). "Our prior work reported that RARα agonist treatment can augment CD38 expression, leading to acquired lung cancer resistance in mice to anti-PD-L1 therapy." (PMID 37689790, 2023). "CD38 is upregulated in mouse models of lung cancer and melanoma that have acquired resistance to anti‐PD‐1/anti‐PD‐L1 blockade, and correlates with CD8+ T‐cell impairment." (PMID 36251503, 2023). "Lastly, our group revealed that tumor-expressing CD38 promotes anti–PD-1 resistance in KP lung cancer; therefore, we also examined the expression of CD38 in the 344SQPD1R models." (PMID 37655662, 2023). "An elevated level of PB CD38+CD8+ MAIT cells were associated with reduced PFS, indicating an active role in lung cancer." (PMID 35371315, 2022). "There are also reports that CD38 knockout suppresses tumorigenesis in mice and the clonogenic growth of human lung cancer cells." (PMID 35625403, 2022). "In contrast, Bu X suggested that knocking out of CD38 in lung cancer cells resulted in an upregulation of NAD+, which led to increasing CD8 + T cell infiltration and predicted a better prognosis." (PMID 34226519, 2021). "In lung cancer, CD38 expression promotes cell growth by fortifying the cells’ anchorage ability, invasion, and xenograft growth in nude mice." (PMID 34572431, 2021).
lung carcinoma (continued). "This is consistent with results obtained with lung cancer cell lines and patient specimens that show increased levels of CD38 mRNA and protein expression of CD38." (PMID 33727923, 2021). "Our clinical data showed that the upregulation of tumor-originated CD38 was correlated with poor survival of lung cancer patients." (PMID 34226519, 2021). "Blocking CD38 led to a significant decrease in T regs within TME of an in vivo mouse model of lung cancer." (PMID 33727923, 2021). "The limited data in melanoma, glioma, esophageal, cervical, and lung cancers indicate an immunosuppressive role for CD38." (PMID 33629216, 2021). "Using multiple in vitro assays we found that the enzymatic activity of tumor expressed-CD38 facilitated lung cancer cell migration, proliferation, colony formation, and tumor development." (PMID 34226519, 2021). "To clarify the roles of CD38 in lung cancer, we constructed CD38 knocked out (KO) cells, CD38 mutant cells (A549-CD38 and LLC-CD38 mutant cell, MU), and CD38 overexpressed cells (OE)." (PMID 34226519, 2021). "CD38 is also involved in the control of nonsmall cell lung cancers (NSCLS), which cover 85% of lung cancers." (PMID 33727923, 2021). "For example, in mouse models targeting the CD38 and PD-1 pathway in MM, lung cancer, and colon adenocarcinoma, the combination of a CD38 antibody and PD-1 antibody resulted in enhanced anti-tumor activity, when compared to targeting either pathway alone." (PMID 32138182, 2020). "A study also certified that in human lung cancer CD38 protein is highly expressed in CD8+ tissue-resident memory cells, CD103+ (TRM cells), and a high density of TRM cell infiltration predicts a better prognosis." (PMID 32425977, 2020). "We demonstrated that the expression of CD38 on lung cancer cells is a novel avenue of acquired resistance to single agent PD-1 checkpoint inhibition." (PMID 31878283, 2019). "Lastly, this study demonstrated CD38 protein and RNA upregulation in a percentage of human lung cancer specimens." (PMID 31878283, 2019). "Research on the influence of CD38 in lung cancer has focused on tumor-expressing CD38 and how it impacts disease progression." (PMID 31878283, 2019). "Knockout of CD38 in human A549 cells reduced the invasive and clonogenic abilities, as well as significantly reducing tumor growth in a xenograft model of lung cancer." (PMID 31878283, 2019). "Overall, a more effective anti-tumor response occurred with blockade of CD38 in this model of lung cancer, and similar effects have been shown though direct NAD+ injection." (PMID 31878283, 2019). "Blocking CD38 in vivo in a mouse model of lung cancer led to a significant reduction of the total Treg cell population within the TME, potentially due to expression of CD38 on these cells and/or occurring through NAD+ accumulation and Treg cell death." (PMID 31878283, 2019). "As expected, enhanced antitumor activity was observed when a CD38 antibody was combined with a PD-L1 inhibitor in this lung cancer mouse model." (PMID 30294326, 2018). "For example, in MM, lung cancer, and colon adenocarcinoma mouse models targeting the CD38 and PD-1 pathway with the combination of a CD38 antibody and PD-1 antibody resulted in enhanced anti-tumor activity, when compared to targeting either pathway alone." (PMID 30294326, 2018). "The combination therapy of anti-PD-L1 and anti-CD38 demonstrated a dramatic therapeutic benefit on primary lung cancer tumor growth and metastasis." (PMID 30505301, 2018). "We analyzed the expression of CD24 and CD38 as two potent biomarkers of lung cancer stem cells and EpCAM and ALDH that are used as biomarkers of a wide range of cancer stem cells." (PMID 22592563, 2013). "In the current study we have assessed the validity of some of the most discussed potential biomarkers of NSCLC, including CD38, in a panel of lung cancer cell lines in search of potent prognostic markers and signature phenotypes for NSCLC." (PMID 24094028, 2013).
lung carcinoma (continued). "Our data indicate that CD38 plays a critical role in lung cancer development and that anti‐CD38 may have therapeutic potential in lung cancer." (PMID 38545257, 2024). "Overall, our data supports the role of CD38 in the development of lung tumors in humans, and anti‐CD38 therapy may have therapeutic potential in lung cancer." (PMID 38545257, 2024). "Also, it was found that the enzymatic activity of tumor-expressed CD38 promotes the migration, proliferation, colony formation, and tumor development of lung cancer cells." (PMID 38533509, 2024). "Indeed, in keeping with our observations in PMs, the proliferating CD8+ cells found in ICI-responsive lung cancer patients co-expressed PD-1, HLA-DR and CD38." (PMID 38384469, 2024). "Neoantigen DCs vaccine combined with anti‐CD38 and CpG, could produce antitumor immunity against ICIs‐resistant mouse lung cancer cell lines." (PMID 37799808, 2023). "Indeed, CD38 expression has been shown to describe a subgroup of CD8+ T cells reinvigorated by anti-PD-1 blockade in human lung cancer." (PMID 36428727, 2022). "Importantly, we discovered a statistically positive association between accumulation of CD38+CD8+MAIT cells and reduced progression-free survival of lung cancer patients." (PMID 35371315, 2022). "Expression of CD38 by lung cancer and other solid tumors may also contribute to an oncogenic tumor microenvironment by promoting the enzymatic conversion of NAD+ to immunosuppressive adenosine." (PMID 36405759, 2022). "In addition, CD38 mRNA and protein were found to be over-expressed in human lung cancer cell lines and lung cancer specimens." (PMID 34211854, 2021). "In summary, our results demonstrated that CD38 mediated tumor cell progression through CD38-cADPR signaling and blockade this axis might potentially serve as a novel therapeutic intervention for lung cancer." (PMID 34226519, 2021). "However, the development of malignancy in lung cancer was reduced with the deletion of ADP-ribose-acceptor hydrolase (ARH)-1 from the CD38 gene." (PMID 34572431, 2021). "Indeed, a recent study showed that CD38 is upregulated on lung cancer cells following blockade of the PD-1/PD-L1 pathway." (PMID 33321969, 2020). "In addition, CD38 is aberrantly expressed in various types of tumors including lung cancer." (PMID 38545257, 2024). "Interestingly, Chen and colleagues report that CD38 blockade could rescue lung cancer mouse models from acquired anti-PD-1 therapy resistance." (PMID 37377962, 2023). "Given this and our prior work, it was hypothesized that an RARα antagonist (IRX6696) would cooperate with anti-PD-L1 therapy to elicit an anti-tumor response to a previously resistant syngeneic lung cancer by reducing CD38 expression and thereby conferring anti-neoplastic effects." (PMID 37689790, 2023). "The focus of this review will be on the role of CD38 in hyper-inflammatory and chronic diseases in the lung such as airway hyper-responsiveness and asthma, as well as how these findings relate to the breadth of research on CD38 functioning within solid tumors including melanoma and lung cancer." (PMID 31878283, 2019). "To explore the potential mechanism by which CD38 regulates lung cancer development, we performed migration and invasion assays to examine its ability to induce EMT in CD38‐overexpressed NSCLC cells." (PMID 38545257, 2024). "PD-1+CD8+ T cells that proliferate in the peripheral blood of lung cancer patients receiving PD-1 therapy express CD28, CD38 and HLA-DR." (PMID 37881432, 2023). "For example, studies have shown that increased expression of CD38 helps prostate cancer cells exhibit stem-like characteristics and helps CD133 + CXCR4 + lung cancer stem cells evade immune surveillance." (PMID 35906622, 2022).
lung carcinoma (continued). "The previous studies indicated that, in lung cancer and renal cell carcinoma patients receiving ICI therapy, CD8 + T cells with effector-like phenotypes (HLA-DR+, CD38+) proliferated, while HLA-DR + CD3 + T cells increase after ICI therapy across various types of tumors, aligning with our results." (PMID 39026211, 2024). "The highly expressed CD38 converts NAD + to adenosine through the CD203a/CD73 complex and adenosine binds and activates its receptor A2AR, inducing the expression of Snail and promoting the invasion and metastasis of lung cancer cells." (PMID 38545257, 2024). "The CD38‐adenosine‐A2AR axis, in turn, regulates Snail‐dependent lung cancer cell EMT." (PMID 38545257, 2024). "To investigate in vitro the immunosuppressive ability of MICs, we derived lung spheroids from cultures of adherent lung cancer cell lines, showing enrichment in CD133+CXCR4+MICs, and increased expression of CD73 and CD38, an enzyme that also concurs in adenosine production." (PMID 33123122, 2020). "We did not observe any RNA expression for CD24 in H661 and SK-MES cell lines, and no quantifiable CD38 RNA expression was seen in the lung cancer cell lines that were CD38-/low by flow cytometry." (PMID 24094028, 2013). "We then tested two potential biomarkers of H460-derived lung cancer stem cells, CD24 and CD38." (PMID 22592563, 2013). "Firstly, patients with lung cancer treated with PD-1 inhibitors have a highly specific subset of proliferating CD8+ T cells in the peripheral blood, expressing effector-like phenotypes (HLA-DR+, CD38+, Bcl-2lo), costimulatory molecules (CD28, CD27, ICOS), and high levels of PD-1." (PMID 35484541, 2022). "Indeed, the clinical outcomes of lung cancer patients treated with combining PD-L1 and CD38 antibody are not satisfactory." (PMID 34226519, 2021). "However, it is not clear whether the CD38‐adenosine‐A2AR signaling pathway is involved in lung cancer invasion and progression, and its potential molecular mechanism is not very clear." (PMID 38545257, 2024). "In our vitro experiments, we observed that CD38 KO and MU cells exhibited an inhibition of cell proliferation, colony formation and migration but an increasing rate of apoptosis in both A549 and LLC lung cancer cells, and the overexpression of CD38 could rescue the ability of cell survival." (PMID 34226519, 2021). "Lung cancer patients displayed a high concentration of CD4+, CD8+, and activated CD38+CD8+MAIT cells, and a decrease of PD1+ double negative (DN) MAIT cells in peripheral blood." (PMID 35371315, 2022).
melanoma (46 papers, 2013 to 2026). A malignant, usually aggressive tumor composed of atypical, neoplastic melanocytes. "CD3D, a marker of T cells relevant to adaptive immunity as well as associated with a favorable prognosis of melanoma, whereas CD38, which regulates NAD+ metabolism, marks activated B cells and plasma cells." (PMID 41271007, 2025). "Kaplan-Meier analysis revealed that loss of CD38 significantly prolonged survival of melanoma-bearing mice (median survival of Cd38‒/‒ mice was 26 days versus 19 days of WT mice)." (PMID 30159123, 2018). "Loss of CD38 in the TME as well as inhibition of its enzymatic activity restrained outgrowth of primary melanoma generated by two transplantable models of melanoma, B16F10 and Ret-mCherry-sorted (RMS) melanoma cells." (PMID 30159123, 2018). "The results show that loss of CD38 substantially and significantly reduced RMS melanoma tumor volume (7.6-fold reduction in Cd38‒/‒ mice at 14 days post-injection) and prolonged survival of the RMS melanoma-bearing mice." (PMID 30159123, 2018). "This conclusion is based on the following findings: i) Loss of CD38 inhibited primary melanoma outgrowth in two different mouse models." (PMID 30159123, 2018). "The effect of CD38 targeting on B16F10 tumor progression involved increased cell death and reduction in the amount of CAFs and blood vessels, suggesting that loss of CD38 affects melanoma outgrowth through these effects." (PMID 30159123, 2018). "iv) Loss of CD38 inhibited the progression of brain tumors generated by intracranial injection of B16F10 or RMS melanoma cells." (PMID 30159123, 2018). "A breakthrough in the field was obtained by Don L. Gibbons and his team, who reported that mouse models of tumors (melanoma and lung cancer), when treated for a long period with anti-PD-1 or anti-PD-L1 therapy, developed acquired resistance that is causally related to CD38 upregulation." (PMID 36078044, 2022). "A study found that untreated control mice formed well vascularized tumors and developed lung metastasis compared with melanoma-infected mice treated with the NAADP inhibitor Ned-19, suggesting that targeted CD38 inhibition in melanoma is partly caused by reduced NAADP production." (PMID 35251964, 2022). "Moreover, CD38 over- expression by cancer-associated fibroblast has been suggested to promote a pro-tumoral activity in melanoma." (PMID 36405759, 2022). "How does loss of CD38 in the melanoma TME reduce tumor outgrowth?" (PMID 30159123, 2018). "We show here that loss of CD38 inhibited melanoma metastasis." (PMID 30159123, 2018). "Given the effect of loss of CD38 on primary melanoma, we next examined whether loss of CD38 may also inhibit occurrence of metastases." (PMID 30159123, 2018). "Indeed, at least in the brain, loss of CD38 inhibited the growth of intracranially injected melanoma cells." (PMID 30159123, 2018). "Importantly, in addition to inhibiting outgrowth of primary melanoma tumors, loss of CD38 also inhibited spontaneous occurrence of RMS pulmonary and brain metastasis." (PMID 30159123, 2018). "Thus, loss of CD38 inhibits melanoma outgrowth in two independent melanoma models." (PMID 30159123, 2018). "There is evidence of CD38 expression within the tumor microenvironment of solid tumors, including melanoma." (PMID 41445795, 2025). "As CD38 upregulation has been considered a possible mechanism of acquired resistance to CPI therapy in patients with melanoma, it is possible that greater levels of CD38 expression are a prerequisite for modakafusp alfa activity in this setting." (PMID 41445795, 2025). "In YUMM1.7 melanoma-bearing mice, small-molecule CD38 inhibition selectively destabilizes intratumoral Tregs, sparking robust antitumor immunity." (PMID 40117361, 2025). "The overexpression of CD3D and CD38 in sEV of melanoma patient lymphatics reflects critical changes in immune cell composition and activity within the SLN." (PMID 41271007, 2025).